FLT3 (fms related receptor tyrosine kinase 3)
Diseases named in the same sentence as FLT3 in open-access papers (continued):
Sharing a sentence is not in itself a finding about the gene and the disease.
Rett syndrome (2 papers, 2021 to 2023). A severe neurodevelopmental disorder affecting the central nervous system. "Kinase inhibitors (BIO—targeting GSK3ß; KW-2449—targeting FLT3) were used to effectively treat a preclinical Rett Syndrome model." (PMID 34707084, 2021). "Moreover, FLT3 inhibitors have been found to have a therapeutic effect in (human) cell and mouse models of Rett syndrome, a genetically determined neurodevelopmental disorder, and to alleviate peripheral neuropathic pain in mice." (PMID 36674940, 2023).
sweet syndrome (2 papers, 2023 to 2025). "AFND/Sweet’s syndrome has been described with other FLT3 inhibitors previously as a manifestation of terminal differentiation of FLT3-mutated blasts." (PMID 37835461, 2023). "Although Sweet syndrome, and less frequently pyoderma gangrenosum, are associated with AML, FLT3 mutations, including internal tandem duplication (ITD) and tyrosine kinase domain (TKD) mutations, are frequently observed in AML-M2 and AML-M4." (PMID 40091927, 2025). "However, some cases of DS with gilteritinib had concomitant rash or AFND/Sweet’s Syndrome, similar to other FLT3 inhibitors." (PMID 37835461, 2023).
thrombosis (2 papers, 2021). "Using multivariate analysis, the risk factors of venous thrombosis in APL were CD15 (P = 0.043), PAI-1 4G4G (P = 0.009), WT-1 (P = 0.043) and FLT3/ITD (P = 0.013), respectively." (PMID 34130694, 2021). "Moreover, in Multivariate Cox Proportional Regression, the risk factors of venous thrombosis in APL were WT-1 (P = 0.043, OR 9.14, 95% CI 1.072-77.825) and FLT3/ITD (P = 0.013, OR 21.89, 95% CI 1.938-247.176), respectively." (PMID 34130694, 2021).
Tourette syndrome (2 papers, 2022 to 2024). A neurologic disorder caused by defective metabolism of the neurotransmitters in the brain. "They find increased expression of FLT3 in the dorsolateral prefrontal cortex and the lymphoblastoid cell lines in patients with Tourette’s Syndrome, and report dysregulation of FLT3 across several brain regions." (PMID 35354918, 2022).
amebiasis (1 paper, 2022). A parasitic infectious disorder caused by amoebas. "However, some factors thought to be important for dcMO development (i.e., Flt3, Pou2f2, Pid1, and Hpgd) were strongly downregulated while their expression by monocytes from the amebiasis model was comparably higher." (PMID 36010615, 2022).
anxiety disorder (1 paper, 2023). A category of psychiatric disorders which are characterized by anxious feelings or fear often accompanied by physical symptoms associated with anxiety. "Studies have supported that peripheral FLT3, as a vital upstream neuromodulator of spinal microglial proliferation, is involved in central pain sensitization, which will cause excessive pain-related behaviors and depressive and anxiety disorders." (PMID 36914737, 2023).
aortic valve disease (1 paper, 2023). "By targeting FLT3 protein and inhibiting FLT3 phosphorylation, ATL I can inhibit the activation of PI3K/AKT pathway, reduce the production of HIF1-α, and inhibit the osteogenic differentiation of VIC, which has the effect of treating calcified aortic valve disease." (PMID 37241729, 2023).
aplastic anemia (1 paper, 2025). Anemia resulting from bone marrow failure (aplastic or hypoplastic bone marrow). "Inactivating FLT3 variants have been less frequently described in non-malignant, autoimmune disorders and are uncommon in aplastic anemia (AA)." (PMID 39773519, 2025).
asthma (1 paper, 2020). "First, we examined the phenotype of asthma in the ovalbumin (OVA)-induced asthma model of wild-type (WT) and Flt3 KO mice." (PMID 33327561, 2020). "Furthermore, to confirm the Th2-inducing effect of BMDCs from Flt3 KO mice in vivo, we used an asthma model via the adoptive transfer of OVA-loaded BMDCs (OVA-BMDCs)." (PMID 33327561, 2020). "However, Flt3-deficient mice have not been investigated in detail using asthma models." (PMID 33327561, 2020). "Since DCs—independent of the Flt3 signal—were sufficient to induce asthma upon OVA challenge in Flt3 KO mice, we hypothesized that Flt3-independent DCs (DCs from Flt3 KO mice) could better induce type 2 immune responses than Flt3-dependent DCs (DCs from WT mice)." (PMID 33327561, 2020).
astrocytic tumor (1 paper, 2021). A glial tumor of the brain or spinal cord showing astrocytic differentiation. "In GBM, mRNA expression of FLT3 and its natural ligand FLT3L is detected in astrocytic tumors as well as GBM cell lines; however, the exact mechanism by which FLT3 contributes to GBM occurrence/progression remains unknown." (PMID 33673213, 2021).
autoimmune thyroid disease (1 paper, 2024). Inflammatory disease of the thyroid gland due to autoimmune responses leading to lymphocytic infiltration of the gland. "The rationale for including such SNPs was to model highly penetrant variants in genes such as NOD2 in CD25 or FLT3 in autoimmune thyroid disease, which play an important role in differentiating these diseases from otherwise genetically related conditions." (PMID 38703768, 2024).
B-cell neoplasm (1 paper, 2021). A group of heterogeneous lymphoid tumors generally expressing one or more B-cell antigens or representing malignant transformations of B-lymphocytes. "CML, FMS-like tyrosine kinase 3 (FLT3)-mutated AML and B-cell neoplasms are amongst the malignancies most responsive to KI treatment, including FDA approved drugs." (PMID 34683897, 2021).
bruxism (1 paper, 2025). Excessive clenching of the jaw and grinding of the teeth. "Among them, gingival overgrowth, oral ulcer, and bruxism were all associated with both biomarkers, suggesting possible synergistic effects between TLR4 and FLT3." (PMID 40362543, 2025).
Burkitt lymphoma (1 paper, 2013). A rare form of malignant mature B-cell non-Hodgkin lymphoma. "Therefore, we first screened different CRC cell lines for c-KIT, FLT3 and MSCF expression in comparison to the Burkitt lymphoma cell line Daudi." (PMID 23900414, 2013).
cardiomyopathies (1 paper, 2021). "There is increasing evidence that FLT3 tyrosine kinase inhibitors are associated with cardiovascular toxicities, such as cardiomyopathies and QT prolongation in cancer clinical trials." (PMID 34686212, 2021).
Central hypothyroidism (1 paper, 2024). A type of hypothyroidism due to an insufficient stimulation of an otherwise normal thyroid gland. "Although the mechanism of gilteritinib-induced endocrine grand disruption remains elusive, in our patient, FLT3 inhibitors caused secondary hypoadrenocorticism and central hypothyroidism, and over time after discontinuation, symptoms improved and hormone levels recovered." (PMID 39473682, 2024).
chondrosarcoma (1 paper, 2020). A malignant cartilaginous matrix-producing mesenchymal neoplasm arising from the bone and soft tissue. "Nevertheless, the epigenetics compound screens identified several other classes of interesting drug targets for both IDH wildtype and IDH mutant chondrosarcoma, among which inhibitors against Aurora kinases, FLT3, HDAC, and JAK showed the most pronounced effect on chondrosarcoma cell growth." (PMID 33266275, 2020).
clear cell sarcoma of kidney (1 paper, 2020). A rare pediatric sarcoma affecting the kidney. "Intragenic tandem duplication is a well-known mechanism to activate oncogenes, for example, FLT3 internal tandem duplication (ITD) in acute myeloid leukemia and BCOR ITD in clear cell sarcoma of kidney (CCSK)." (PMID 32490123, 2020).
Coagulopathy (1 paper, 2011). "Coagulopathy was significantly more prevalent among FLT3 mutated cases (p=0.037)." (PMID 22220250, 2011).
colitis (1 paper, 2014). Inflammation of the colon. "In this study, we observe the disease activity index (DAI) and histological scoring, detect the amounts of DCs and T-regs and expression of Flt3/Flt3L, and investigate Flt3/Flt3L participating in the process of DCs regulating T-regs in DSS-induced colitis." (PMID 25371672, 2014). "Our findings suggest that the reduction of Flt3 and Flt3L expression may possibly induce colonic immunoregulatory imbalance between CD103+MHCII+DCs and CD4+CD25+FoxP3+T-regs in DSS-induced colitis." (PMID 25371672, 2014). "In conclusion, the reduction of Flt3 and Flt3L expression may possibly induce colonic immunoregulatory imbalance between CD103+MHCII+DCs and CD4+CD25+FoxP3+T-regs in DSS-induced colitis." (PMID 25371672, 2014).
deafness (1 paper, 2017). An inherited or acquired condition characterized by the complete loss of the ability to hear from one or both ears. "While Flt3 and c-Kit have not previously been implicated in HC damage, rare cases of deafness following c-Kit inhibition in patients has been reported." (PMID 29049311, 2017).
dyskeratosis congenita (1 paper, 2022). Dyskeratosis congenita (DC) is a rare ectodermal dysplasia that often presents with the classic triad of nail dysplasia, skin pigmentary changes, and oral leukoplakia associated with a high risk of bone marrow failure (BMF) and cancer. "The constellation of clinical features and strong family history along with del 7 and FLT3-TKD AML with preceding MDS highly suggests a germline predisposition state dyskeratosis congenita." (PMID 36278519, 2022).
epilepsy (1 paper, 2024). A brain disorder characterized by episodes of abnormally increased neuronal discharge resulting in transient episodes of sensory or motor neurological dysfunction, or psychic dysfunction. "Morphological changes between P0 and P7 suggest that FLT3+IBA1+ cells start from an ameboid shape to adopt a microglia-like morphology, something typically seen after at least 2 days of infiltration in an animal model of epilepsy to support microglia in their pruning endeavors." (PMID 39021809, 2024).
erythroleukemia (1 paper, 2024). Acute erythroid leukemia characterised by the presence of at least 50% erythroid precursors and at least 20% myeloblasts in the bone marrow.
Fanconi anemia (1 paper, 2021). Fanconi anemia (FA) is a hereditary DNA repair disorder characterized by progressive pancytopenia with bone marrow failure, variable congenital malformations and predisposition to develop hematological or solid tumors. "A novel compound CAR-T targeting both CD33 and CLL-1 was tested in a phase I study in which a 6 year-old female with Fanconi’s anemia-associated juvenile myelomonocytic leukemia carrying FLT3-ITD mutation that had been heavily treated with multiple therapies, including a FLT3 inhibitor." (PMID 33669431, 2021).
gram-negative bacterial infections (1 paper, 2025). Infections caused by bacteria that show up as pink (negative) when treated by the gram-staining method. "The role of dendritic cells was noteworthy considered in Gram-negative bacterial infections triggering the cytokine, Interleukin, GPCR, IFN, FLT3, EGFR, G alpha, Receptor tyrosine kinase, and TLR signaling pathways and exacerbating their activities by the MQs and VSMCs in vessel microenvironment." (PMID 40275124, 2025).
Granuloma (1 paper, 2025). A compact, organized collection of mature mononuclear phagocytes, which may be but is not necessarily accompanied by accessory features such as necrosis. "A diverse array of innate immune cells, including mast cells (MC) (cluster 20: HDC, CPA3, KIT), dendritic cells (DC) (cluster 23: CLNK, WDFY4, FLT3), neutrophils (FCGR3B, FFAR2, CSF3R), and macrophages (CD68, CD163, C1QA/B/C), was also present in these granulomas." (PMID 40772762, 2025).
Graves disease (1 paper, 2022). Graves' disease is an autoimmune disorder that leads to overactivity of the thyroid gland (hyperthyroidism).It is caused by an abnormal immune system response that causes the thyroid gland to produce too much thyroid hormones.
gynecological cancer (1 paper, 2024).
hyperthyroidism (1 paper, 2014). Overactivity of the thyroid gland resulting in overproduction of thyroid hormone and increased metabolic rate. "To the best of our knowledge, this is the first case report of hyperthyroidism concurrent with FLT3-ITD-positive APL, and we hypothesize that the translocated genetic abnormity involving the c-erb-A protooncogene may play a major role in the leukemogenesis." (PMID 24396459, 2014).
hyperuricemia (1 paper, 2025). An abnormally high level of uric acid. "For example, in hyperuricemia, we identified ADR-DP proteins that included PDGFRA, FLT3, and ABL1 as having high values in the z axis." (PMID 39954672, 2025).
Hypoalbuminemia (1 paper, 2021). The concentration of albumin in the blood circulation is below the lower limit of normal. "Previous studies reported that these factors increased the risk of APL thrombosis, including male, high score performance status (PS), high white blood cell count and platelet count, low fibrinogen levels, hypoalbuminemia, PML/RARa fusion gene variant, CD2/CD15 and FLT3-ITD positive." (PMID 34130694, 2021).
injury (1 paper, 2023). Damage inflicted on the body as the direct or indirect result of an external force, with or without disruption of structural continuity. "Moreover, lestaurtinib, a janus kinase and fms-like tyrosine kinase 3 (FLT3) inhibitor, was shown to attenuate acute lung injury by reducing neutrophil infiltration, which may also attenuate brain edema by inhibiting the JAK2/STAT3 pathway." (PMID 37234258, 2023).
ischemia (1 paper, 2018). A hypoperfusion of the BLOOD through an organ or tissue caused by a PATHOLOGIC CONSTRICTION or obstruction of its BLOOD VESSELS, or an absence of BLOOD CIRCULATION. "We found that mice deficient in Flt3 or mice that received an Flt3 inhibitor (AC220) showed significantly reduced areas of ischemia-induced retinal neovascularization (RNV) and laser-induced choroidal NV (CNV) (P < 0.05)." (PMID 29854425, 2018).
lung fibrosis (1 paper, 2025). "Additionally, FLT3LG and FLT3 have been implicated in kidney and splenic fibrosis in mouse models, although their connection to lung fibrosis remains underexplored." (PMID 40165483, 2025).
lymphatic system disorder (1 paper, 2026). A disease involving the lymphatic part of lymphoid system. "The most frequently reported adverse events (AEs) were classified under the System Organ Class (SOC) Blood and lymphatic system disorders (N = 5474, 58.4% of them related to FLT3 inhibitors)." (PMID 41729312, 2026).
mast cell disease (1 paper, 2022). "Although the prevalence of FLT3 mutations is high in human AML, it is not presented in systemic mast cell disease." (PMID 36072760, 2022).
monoclonal gammopathy of undetermined significance (1 paper, 2020). "FLT3 expression was analyzed in bone marrow biopsies of patients with monoclonal gammopathy of undetermined significance or smoldering myeloma (MGUS, SMM), newly diagnosed MM (NDMM), and relapsed/refractory MM (RRMM) by immunohistochemistry (IHC)." (PMID 32825035, 2020).
nasopharyngeal carcinoma (1 paper, 2022). A carcinoma arising from the nasopharyngeal epithelium. "We previously found that the FLT3 inhibitors sorafenib and sunitinib blocked the signalling pathways of tumour cell proliferation and induced apoptosis of nasopharyngeal carcinoma cells." (PMID 35246156, 2022). "The combined administration of FLT3 inhibitors and NK cells achieved synergistic killing in nasopharyngeal carcinoma and hepatocellular carcinoma." (PMID 35246156, 2022).
non-Hodgkin lymphoma (1 paper, 2022). Distinct from Hodgkin lymphoma both morphologically and biologically, non-Hodgkin lymphoma (NHL) is characterized by the absence of Reed-Sternberg cells, can occur at any age, and usually presents as a localized or generalized lymphadenopathy associated with fever and weight loss. "However, other researchers found that FOXO1 promoted resistance of non-Hodgkin lymphomas to anti-CD20-based therapy and played a tumor-promoting role in FLT3-ITD+ AML through a complex mechanism, respectively." (PMID 36290822, 2022).
Noonan syndrome (1 paper, 2016). Noonan Syndrome (NS) is characterized by short stature, typical facial dysmorphism and congenital heart defects. "Germline PTPN11 mutations cause Noonan syndrome, therefore this patient may present with RASopathy-related phenotypes given that somatic mutations in FLT3 and PTPN11 activate the Ras/MAPK pathway and are largely mutually exclusive in ALL." (PMID 27683039, 2016).
oral diseases (1 paper, 2025). "In the “biomarkers-oral diseases” network, TLR4 was associated with 69 oral diseases, and FLT3 was associated with 35 oral diseases." (PMID 40362543, 2025).
osteosarcoma (1 paper, 2020). A usually aggressive malignant bone-forming mesenchymal neoplasm, predominantly affecting adolescents and young adults. "Furthermore, we showed that TAS‐115 inhibited the phosphorylation of PDGFRα, AXL, and FLT‐3 and decreased cell proliferation in LM8 and other human osteosarcoma cell lines." (PMID 32128992, 2020).
parathyroid cancer (1 paper, 2021). "LINC00959 and lnc-FLT3–2:2 may participate in parathyroid cancer through downregulating FLT1." (PMID 33910638, 2021).
Peri-Implantitis (1 paper, 2025). An inflammatory process with loss of supporting bone in the tissues surrounding functioning DENTAL IMPLANTS. "Studies have identified key differentially expressed genes (e.g., TLR4, CXCL8, FLT3, and IL1B), immune cell infiltration profiles (e.g., CD4+ T cells and macrophages), and microbiome signatures (e.g., distinct Fusobacterium nucleatum clades) in peri-implantitis." (PMID 40981185, 2025).
pneumococcal pneumonia (1 paper, 2021). A febrile disease caused by STREPTOCOCCUS PNEUMONIAE. "Pretreatment of mice with FLT3L increased lung injury during pneumococcal pneumonia, likely through inducing accumulation of proinflammatory dendritic cells, and pharmacological inhibition of FLT3 signaling attenuated LPS-induced lung injury and edema in mice." (PMID 34054832, 2021).
pulmonary edema (1 paper, 2022). Accumulation of fluid in the lung tissues causing disturbance of the gas exchange that may lead to respiratory failure. "We found that ibrutinib effectively suppressed poly I:C- and LPS-induced pulmonary edema, pro-inflammatory cytokine release, histopathological changes, neutrophil aggregation, lymphocyte aggregation, and activation of the BTK-, FLT3-, and EGFR-related signaling pathways." (PMID 36362264, 2022).
Renal insufficiency (1 paper, 2024). A reduction in the level of performance of the kidneys in areas of function comprising the concentration of urine, removal of wastes, the maintenance of electrolyte balance, homeostasis of blood pressure, and calcium metabolism. "Reasons for not receiving FLT3i treatment included HCT before maintenance therapy was routinely used in 2019 (n = 12), renal insufficiency (n = 1), FLT3-TKD only (n = 3), and early relapse (n = 2)." (PMID 39589497, 2024).
substance dependence (1 paper, 2025). The psychological or physiological need to take a substance in order to experience its effects or to avoid the effects of its absence. "Drugs aimed at ERBB2, FCGR3A, and FLT3 are primarily used in treating various cancers and benign tumors, while ALDH2 is targeted in therapies for a range of systemic diseases, notably cancer and substance dependence." (PMID 40868097, 2025).